CXCL13 (C-X-C motif chemokine ligand 13)
Diseases named in the same sentence as CXCL13 in open-access papers (continued):
Sharing a sentence is not in itself a finding about the gene and the disease.
colorectal cancer (continued). "Validation with a cohort of 23 colorectal cancer (CRC) samples confirms the significant impact of TGF-β1+ CD4+ and CXCL13+ CD4+ and CD8+ T cells on ICB efficacy." (PMID 40054456, 2025). "This study revealed that with advancing TNM staging of colorectal cancer (CRC), TNFRSF18 expression in CD8+ T cells progressively decreased, while CXCL13 expression increased." (PMID 40770837, 2025). "In colorectal cancer (CRC), CXCL13 was detected in both T cells and tumor cells, and CXCL13 deletion characterized with fewer infiltrating TFH and B cells was associated with a higher recurrence rate and poorer survival." (PMID 39001456, 2024). "For this reason, we screened 7 m6A-related genes (IL12RB1, FASLG, CXCL13, GBP2, CXCL10, CXCR6, and CIITA) through WGCNA and LASSO regression in this study and established an m6A-GPI in colorectal cancer." (PMID 37427112, 2023). "The expression levels of VSIG4, ZNF532, MEIS2, and CXCL13 were downregulated, while CXCL10 was elevated between colorectal cancer and normal tissues." (PMID 36909170, 2023). "CXCR5 is the receptor of C-X-C motif chemokine ligand 13 (CXCL13); CXCL13/CXCR5 signaling axis activity can accelerate the progression of colorectal carcinoma by activating the PI3K/AKT pathway." (PMID 38049474, 2023). "For example, in colorectal cancer tissue, CXCL1, CXCL2, CXCL3, CXCL5, CXCL8, and CXCL11 were highly expressed, while CXCL12, CXCL13, and CXCL14 were little expressed." (PMID 36612163, 2022). "The CXCL13/CXCR5 axis is confirmed to facilitate tumor cell growth and metastasis in prostate cancer and colorectal cancer via MAPK and PI3K/AKT signaling pathways." (PMID 36612163, 2022). "This cell state displayed activation (CXCL13) and exhaustion (LAG3, HAVCR2, CD96) markers, which may account for their participation in the immune checkpoint inhibitor sensitivity of MSI-H colorectal cancers." (PMID 35538548, 2022). "Tertiary lymphoid structures (TLS) In colorectal cancer (CRC), tumors lacking CXCL13 have fewer intratumoral B cells and a worse prognosis than those expressing CXCL13." (PMID 39068459, 2024). "Among them, MMP12 was highly expressed in colorectal cancer tissues, while ARMCX2, CEBPA, CXCL13, FABP4, HOXC6, SIGLEC1 and VSIG4 were more expressed in normal tissues than in cancer tissues." (PMID 36544770, 2022).
neurosyphilis (37 papers, 2014 to 2025). Infection of the brain or spinal cord by Treponema pallidum. "Prospective cohort studies involving patients with HIV-associated neurosyphilis have identified CSF CXCL13 levels as a reliable biomarker for active neurosyphilis and a potential tool for monitoring treatment response." (PMID 41011752, 2025). "This underlines the importance of CXCL13 as both a standalone and combinatory biomarker in predicting and managing neurosyphilis, emphasizing its potential for guiding therapeutic strategies and improving patient outcomes." (PMID 40070668, 2025). "The results showed that the diagnostic sensitivity of CSF CXCL13 concentration ≥13.37 pg/mL in neurosyphilis patients was 84.9%, and the specificity was 78.87%." (PMID 36452956, 2022). "Several papers have evaluated CSF CXCL-13, a B-cell chemoattractant, as a diagnostic test for neurosyphilis." (PMID 26286439, 2015). "We hope to further prove whether CXCL13 can be used as an independent diagnostic factor for neurosyphilis by improving previous research." (PMID 41221293, 2025). "Numerous studies have shown that high concentrations of CXCL13 in the CSF may be possible biomarkers of neurosyphilis, especially for asymptomatic neurosyphilis, adding to the growing list of diagnostic molecular markers for syphilis." (PMID 38105236, 2023). "CXCL13 has recently been published as a diagnostic marker for neurosyphilis." (PMID 37868301, 2023). "However, it is noteworthy that the sensitivity and specificity of CSF CXCL13 are different in neurosyphilis due to the different diagnostic criteria, population characteristics and cut-off values of CSF CXCL13." (PMID 36452956, 2022). "Therefore, the aim of this study was to conduct a review of the current literature regarding CXCL13 in serum and CSF to determine its diagnostic significance in spirochetal neurological diseases neuroborreliosis and neurosyphilis." (PMID 32331231, 2020). "In Marra’s paper, she indicated that CSF CXCL13 ≥ 10 pg/mL could be used as a diagnostic indicators for symptomatic neurosyphilis characterized by high sensitivity (90 %) but low specificity (37 %)." (PMID 27376011, 2016). "To investigate whether there are particular types of neurosyphilis that are associated with CXCL13 production, we further analyzed the serum and CSF concentrations of CXCL13 in different types of neurosyphilis." (PMID 27376011, 2016). "The finding that more than 95% of our patients had a CSF CXCL13 concentration of more than 10 pg/mL also supports the guidelines of the CDC that all patients with ocular syphilis should be treated for neurosyphilis." (PMID 38983560, 2022). "In patients with ocular syphilis and neurosyphilis the AH/serum ratios for CXCL13, CXCL10 and CXCL8 were consistently higher than those in patients with ocular syphilis but no neurosyphilis." (PMID 38983560, 2022). "Increased concentrations of the chemokines CXCL13, CXCL8, and CXCL10 in the CSF or their CSF/serum ratio, particularly in the case of CXCL13, can predict the occurrence of neurosyphilis." (PMID 36687428, 2022). "Above these values CSF CXCL13 was 85.4% sensitive and 89.1% specific for diagnosing neurosyphilis, and CXCL10 and CXCL8 were both 79% sensitive, with a specificity of 90.1% and 91.1%, respectively." (PMID 38983560, 2022). "Among these biomarkers, CXCL13 has been used as an auxiliary reference for the diagnosis of neurosyphilis in the latest guidelines in China but still falls short for application in clinical diagnosis." (PMID 36687428, 2022). "It was found that CSF CXCL13 ≥250 pg/mL had a sensitivity of 41% for both asymptomatic and symptomatic neurosyphilis and a specificity of 93 and 79%, respectively." (PMID 36452956, 2022). "The addition of CXCL13 analysis in the routine testing of our patients would have resulted in 4 more patients being diagnosed with neurosyphilis." (PMID 38983560, 2022).
neurosyphilis (continued). "At present, CSF CXCL13 is considered to be a potential indicator of the antibiotic treatment response and is used to evaluate the effectiveness of treatment for neurosyphilis." (PMID 36452956, 2022). "In patients with neurosyphilis, mean AH levels of CXCL13 and CXCL10 were markedly higher than in serum while mean CSF levels of CXCL10 were also markedly higher than in serum." (PMID 38983560, 2022). "Chemokines are the most studied cytokines as potential CSF indicators in neurosyphilis patients, among which CXCL13 has been studied extensively and intensively." (PMID 36452956, 2022). "The CXCL13 concentrations in the CSF decline after treatment for neurosyphilis is initiated and can be used as an indicator for the response to treatment." (PMID 38983560, 2022). "HIV infection can slightly increase CSF CXCL13 concentration, which is negligible in the case of a large increase in CSF CXCL13 concentration in neurosyphilis patients." (PMID 36452956, 2022). "Another study indicated that CSF CXCL13 is more suitable for the diagnosis of neurosyphilis patients with HIV infection." (PMID 36452956, 2022). "They found that using a CSF CXCL13 cut-off value of 10 pg/ml had a significantly higher sensitivity (sensitivity 90%; specificity 37%) for diagnosing symptomatic neurosyphilis than using VDRL tests." (PMID 38983560, 2022). "The level of CXCL13 measured in the AH correlated well with the concentrations found in the CSF of patients with neurosyphilis." (PMID 38983560, 2022). "In this study, we also found elevated CXCL13 levels in the CSF of patients with other infectious CNS diseases, such as neurosyphilis and tuberculous meningitis, which has been reported before." (PMID 34132584, 2021). "The patient with neurosyphilis had CSF CXCL13 concentrations of 500 pg/ml in the CXCL13 ELISA and 982 pg/ml in the recomBead CXCL13 assay." (PMID 34132584, 2021). "At the same time, the highest concentration levels of CXCL13 have been observed in patients with neurosyphilis, meningoencephalitis, or encephalomyelitis in comparison to neurosyphilis patients with cranial nerve palsies and cerebral luetic vasculitis." (PMID 32331231, 2020). "Recent retrospective studies have revealed that CXCL13 levels are increased in the CSF and serum of patients with early and late neurosyphilis." (PMID 32331231, 2020). "Some cases illustrated that levels of CSF IL-10 and CXCL-13 in patients with neurosyphilis elevated significantly." (PMID 33628742, 2020). "A potentially interesting new CSF marker in patients with neurosyphilis is the chemokine CXCL13, which is significantly elevated in the CSF of patients with neurosyphilis." (PMID 33225223, 2020). "Higher concentrations of CSF CXCL13 have been observed in symptomatic neurosyphilis in comparison to asymptomatic neurosyphilis." (PMID 32331231, 2020). "As an example, to differentiate neurosyphilis from other neurological disorders, a cut-off point of 76.3 pg/mL of CXCL13 has been suggested with a sensitivity and specificity of 50% and 90%, respectively." (PMID 32331231, 2020). "In neurosyphilis patients (n = 17), after 3-month treatment, the CSF leukocyte count, IgG index and CXCL13 concentration reduced significantly as compared to those before treatment; they further reduced after 12-month treatment." (PMID 33336020, 2020). "The CSF leukocyte count had a positive relationship with CSF CXCL13 concentration in 17 patients with neurosyphilis (r = 0.8855, p < 0.01)." (PMID 33336020, 2020). "Following treatment for neurosyphilis, CXCL13 declined rapidly in parallel with a WBC count and improvement in clinical symptoms." (PMID 32331231, 2020). "In symptomatic and asymptomatic neurosyphilis patients, the CSF CXCL13 concentrations were 133.5 pg/mL and 90.63 pg/mL, respectively, which were significantly higher than in non-neurosyphilis patients (10.01 pg/mL; P < 0.01)." (PMID 33336020, 2020).
neurosyphilis (continued). "The studies, however, included mostly adult patients with very different symptoms, i.e., asymptomatic HIV, bacterial meningitis, or conditions that also result in a CSF CXCL13 increase, i.e., neurosyphilis or Cryptococcus neoformans infections." (PMID 28859668, 2017). "We then further compared the level of CSF CXCL13 between asymptomatic and symptomatic neurosyphilis patients and found that CSF CXCL13 level in symptomatic neurosyphilis was significantly higher than that in asymptomatic neurosyphilis patients (p = 0.008)." (PMID 27650493, 2016). "Elevated CXCL13 levels were found not only in the CSF of neurosyphilis patients with HIV infection but also in the CSF of patients with multiple sclerosis, acute Lyme neuroborreliosis, clinically isolated syndrome and other inflammatory neurological diseases." (PMID 27376011, 2016). "The number of neurosyphilis cases were also too small to reflect the real situation of CSF CXCL13 in the neurosyphilis." (PMID 27376011, 2016). "Other conditions where elevated CXCL13 levels can be detected include, for example, neurosyphilis and CNS lymphoma." (PMID 27756335, 2016). "That is to say, the study subjects of HIV-negative neurosyphilis patients were too small to represent the CSF CXCL13 results of neurosyphilis patients." (PMID 27376011, 2016). "Of note, the serum CXCL13 level was lower in symptomatic neurosyphilis patients than that in asymptomatic neurosyphilis patients (p = 0.013)." (PMID 27650493, 2016). "In this study, the serum CXCL13 level was significantly higher in neurosyphilis and in syphilis/non-neurosyphilis patients than in healthy volunteers (χ2 = 48.491, P < 0.001; χ2 = 17.170, P < 0.001)." (PMID 27376011, 2016). "In conclusion, our data show that CXCL13, CXCL10 and CXCL8 are potential biomarkers to be used as a complementary diagnostic tool for neurosyphilis." (PMID 27650493, 2016). "ROC analysis revealed that the CSF CXCL13 levels were robust in discriminating patients with neurosyphilis and non-neurosyphilis/syphilis, with an AUC of 0.831 (95 % CI 0.724–0.938, P = 0.000)." (PMID 27376011, 2016). "During the course of treatment, CXCL13 levels rapidly declined in neurosyphilis patients, paralleling the course of WBCs in the CSF." (PMID 25975424, 2015). "CXCL13 levels in the CSF of patients with neurosyphilis can be as high as in patients with LNB, exceeding the proposed threshold of 250 pg/mL for the diagnosis of LNB." (PMID 25975424, 2015). "In our study, neurosyphilis patients with encephalitic and/or myelitic syndromes (e.g., spastic gait, seizures, or aphasia) showed the highest CXCL13 levels in their CSF." (PMID 25975424, 2015). "Median CXCL13 levels at baseline were 972 pg/mL for neurosyphilis patients, 8,000 pg/mL for LNB patients, and 7.8 pg/mL for MS patients." (PMID 25975424, 2015). "The baseline levels of CXCL13 in patients with neurosyphilis showed a high variance, with the highest values observed in patient #5 with meningoencephalitis (7,140 pg/mL) and in patient #3 with encephalomyelitis (6,600 pg/mL)." (PMID 25975424, 2015). "Our main finding is that CXCL13 levels are substantially elevated in CSF from patients with untreated neurosyphilis and can surge as high as previously reported for patients with LNB." (PMID 25975424, 2015). "Other reports have shown different CXCL13 levels in the CSF of patients with neurosyphilis, which were found to be remarkably lower than in CSF samples from patients with LNB." (PMID 25975424, 2015). "A possible association between different neurological manifestations and CXCL13 levels in CSF should be the subject of further prospective investigations in neurosyphilis." (PMID 25975424, 2015). "We investigated retrospectively CXCL13 levels in the cerebrospinal fluid (CSF) of patients with neurosyphilis at initial diagnosis and during treatment." (PMID 25975424, 2015).
neurosyphilis (continued). "Patients with LNB and neurosyphilis showed significantly higher CXCL13 levels in their CSF compared to MS patients (p < 0.05, p < 0.001, respectively)." (PMID 25975424, 2015). "Levels of CXCL13 in the CSF of patients with neurosyphilis declined during antibiotic therapy, in parallel with the clinical improvement of symptoms and a decrease in the WBC count in the CSF, thus representing another marker of CNS inflammation." (PMID 25975424, 2015). "Consequently, monitoring changes in CXCL13 levels serves as a reliable index to evaluate the therapeutic effectiveness in stroke patients with neurosyphilis." (PMID 40070668, 2025). "Notably, neurosyphilis patients exhibited elevated levels of CXCL13 in their cerebrospinal fluid, suggesting a potential mediation of B cell aggregation." (PMID 38694502, 2024). "CXCL13 has other interesting applications, including treatment monitoring in neurosyphilis." (PMID 38105236, 2023). "Neurosyphilis should be considered in the differential diagnosis of limbic encephalitis with lymphocytic pleocytosis in cerebrospinal fluid, and CXCL-13 may help to achieve diagnosis." (PMID 36979313, 2023). "Firstly, it shows that the chemokines measured in the AH of patients with ocular syphilis correlate to the values previously found in the CSF of patients with neurosyphilis, and that patients with ocular syphilis have elevated CSF levels of CXCL13, CXCL10 and CXCL8, as expressed in the mean values." (PMID 38983560, 2022). "Using a CSF CXCL13 value of more than 250 pg/mL independently to make the diagnosis of neurosyphilis, would have resulted in 54% being classified as having neurosyphilis, which correlates with the 56.5% of the study sample who have been diagnosed with neurosyphilis." (PMID 38983560, 2022). "The CSF results of one patient was inconsistent, with a negative FTA Abs for neurosyphilis, but with the other CSF tests indicating neurosyphilis (CSF CXCL13 level of 5600 pg/mL, 44 lymphocytes, 0.95 g/L protein, CXCL13 CSF to serum ratio of 614, serum RPR of 32)." (PMID 38983560, 2022). "In addition, the decrease in the CSF levels of CXCL10 and CXCL8 was consistent with the decrease of CXCL13 levels after treatment for neurosyphilis was initiated." (PMID 38983560, 2022). "Some studies have reported that the CSF TPPA titers and the level of CSF Chemokine ligand 13 (CXCL13) may be factors for the diagnosis of neurosyphilis." (PMID 35669916, 2022). "Using CXCL13 as an example, the overall AH/serum ratio is 3.33 whereas that for patients without concurrent neurosyphilis is only 2.82 and for patients with concurrent neurosyphilis it is 3.78." (PMID 38983560, 2022). "However, the mean CXCL13 concentration in the AH was higher than in the serum of participants with neurosyphilis (p=0.02), while there was only a trend for the mean CXCL13 concentration to be higher in the CSF than the serum in these participants (p=0.07)." (PMID 38983560, 2022). "Therefore, some authors have focused on patients who were co-infected with HIV and neurosyphilis and attempted to investigate CXCL13 levels in these patients." (PMID 32331231, 2020). "Moreover, CSF CXCL13 levels have been shown to be significantly higher in symptomatic and asymptomatic neurosyphilis in comparison to uncomplicated syphilis." (PMID 32331231, 2020). "Other studies have compared CXCL13 concentrations in neurosyphilis and other CNS conditions." (PMID 32331231, 2020). "Furthermore, the odds of symptomatic neurosyphilis with HIV co-infection increase significantly with a rise in CSF CXCL13 levels, white blood cell count, detection of Treponema pallidum, and plasma HIV RNA." (PMID 32331231, 2020). "In contrast, serum CXCL13 levels have been found to be elevated in asymptomatic neurosyphilis." (PMID 32331231, 2020). "Because of the poor sensitivity of the CSF RPR and the low specificity of the CSF TPPA, CSF CXCL13 concentrations may serve as a supplementary biomarker of neurosyphilis." (PMID 27376011, 2016).